IL6 (interleukin 6)
Diseases named in the same sentence as IL6 in open-access papers (continued):
Sharing a sentence is not in itself a finding about the gene and the disease.
infection (continued). "In contrast, the response against ZH501 infection was very broad with onset evident at 48 hpi with significant elevations of IL-6, KC, MCP-1 and MIP-1α." (PMID 22389738, 2012). "This is consistent with other infection models, in which IL-6, a cytokine displaying both pro- and anti-inflammatory properties, has been shown to be upregulated early during infection." (PMID 22455545, 2012). "After infection, bladder epithelia secreted large amounts of pro-inflammatory cytokines, such as IL-6 and chemokine, which are responsible for the vigorous neutrophil response and early clearance of infectious bacteria." (PMID 23056598, 2012). "Clarithromycin inhibits protein and mRNA expression of ICAM induced by infection with the virus and increased levels of proinflammatory cytokines such as IL-1SS, IL-6, and IL-8." (PMID 22969171, 2012). "IL-6, an important proinflammatory cytokine in response to infection, is increased after CLP in mice." (PMID 22835277, 2012). "Starting at day 1 post infection, control animals also had higher levels of several cytokines, including IL-1α, IL-1β, IL-6, IL-12p70, and IFN-γ in plasma, additionally IL-17 and TNF-α and chemokines (KC, MCP-1, MIP-1α) were elevated in lungs." (PMID 22448290, 2012). "Interleukin-6 (IL-6) is an important cytokine involved in the regulation of host response to tissue injury and infection." (PMID 22114600, 2012). "Rapid increase in IL-6 levels is observed during acute inflammatory responses due to injury, infection and stress." (PMID 22321936, 2012). "An infection significantly increased IL-6 secretion to 146 pg/ml and IL-6 secretion increased even further to 235 pg/ml with glucose and to 208 pg/ml with 3,4-DGE." (PMID 22045866, 2012). "Inflammatory and immunologic responses, mediated by increased levels of TH1-type (TNF-α and IFN-γ) and TH2-type cytokines (IL-10 and IL-6), appear to be important for recovery from infection." (PMID 21912565, 2012). "WT mice which received Stat1−/− bone marrow responded to infection with a systemic cytokine storm, i.e elevated serum levels of almost all measured cytokines and chemokines (IL6, IL22, TNFα, MCP1, IL10, Rantes, IP10 and MCP3)." (PMID 22719255, 2012). "It is of note that Il6 which codes for proinflammatory cytokine IL-6, an important regulator of the acute-phase response to injury and infection, was downregulated in Mmp13−/− tissues at both 7 d and 14 d (FC∼1 and FC∼1.2, respectively)." (PMID 22880047, 2012). "We investigated IL-6 expression in humans hospitalized with H1N1pdm infection and further analyzed patient outcome with clinical signs." (PMID 22679491, 2012). "Neutrophil depletion with anti-Ly6G antibody caused a reduction in IL-6 and monocyte chemotactic protein-1 expression upon TDM treatment, and reduced levels of immune cell recruitment during the initial stage of infection." (PMID 22496642, 2012). "This contrasts with our study, where IL-1 or TNF were barely detectable and only IL-6 production was consistently modified by infection." (PMID 23176037, 2012). "As observed for the systemic inflammatory response, early IL-6 levels were significantly reduced at day 1 post infection in kidneys of Ifnar1−/− mice when compared to WT animals." (PMID 22911155, 2012). "Accordingly, we included Tnfα, Ccl2, and Il6 among the genes evaluated with in-vitro infection models." (PMID 23248776, 2012). "In the present study, analysis from cumulative supernatants revealed increases of IL-6 and IL-8 production after 2 and 3 days infection of HeLa cells with C. trachomatis, which were decreased over time in noncumulative supernatants." (PMID 22529524, 2012). "Although transcripts of CXCL1 and MIP-2 chemokines, and IL-6 can be detected in spleen cells one day after infection, their levels are significantly lower than those induced by other bacteria." (PMID 22500859, 2012).
infection (continued). "In accordance with our previous data suggesting aggravation of infection by rhDNase treatment, IL-6 levels were found to rise faster in the rhDNase-treated group, and the highest cytokine concentrations were measured after six hours." (PMID 22835277, 2012). "Microarray analysis of RSV-infected human alveolar type II epithelial (A549) cells reveals that IL-6 mRNA was induced ~20-fold 30 minutes after infection." (PMID 22962966, 2012). "As the infection progressed, C. trachomatis multiplied to form inclusion bodies, subsequently stimulating excessive production of IL-6 and IL-8 as clearly shown in infected J774 cells." (PMID 22529524, 2012). "We demonstrated similar increases in IL-6 production in persistent infections compared to active infections in vitro." (PMID 22894815, 2012). "While for some authors interleukin-6 (IL-6) and IL-18 are markers of active disease or asymptomatic infection; respectively, for others IL-6 and IL-18 have no determinant role." (PMID 21845197, 2012). "In C57BL/6J, BALB/cJ, and B6129SF2/J mice, infection with A/Mexico/4108/2009 (H1N1pdm) consistently triggered severe disease and increased IL-6 levels in both lung and serum." (PMID 22679491, 2012). "Although IL-6 is produced by Th2 cells, it is a proinflammatory cytokine and a major mediator of host response to inflammation and infection." (PMID 22719180, 2012). "The levels of IL-6 also significantly increased by more than 1.5-fold after 3 d.p.i. as well as by 6-fold and 4-folds on after 5 and 7 days post infection respectively, suggesting a robust inflammation upon JEV infection in mice brain." (PMID 22393394, 2012). "Complementary analysis of Il6, Stat3, and Il6ra gene expression by qRT-PCR similarly identified peak upregulation of Stat3 and Il6ra early at day 2 pi, and persistent upregulation of Il6 throughout infection." (PMID 22679491, 2012). "At 12 and 24 hours post-infection, the level of IL-6 induced by NH1125 was at least an order of magnitude greater than that by NH1067." (PMID 22962966, 2012). "From this collection of clinical isolates, we screened both subgroup A and B isolates for their ability to induce the secretion of IL-6 during infection of the pulmonary epithelial cell line A549." (PMID 22962966, 2012). "The presence of infection accentuates the systemic inflammation accompanied the ARF on top of AECOPD which was expressed by elevation of IL-6." (PMID 23724320, 2012). "At 2 h post-infection, only KC (the murine functional homologue of IL-8) and IL-6 were detected, and KC levels in mice infected with 3348ΔspyCEP were significantly higher than in w.t. infected mice (data not shown)." (PMID 22848376, 2012). "It is also possible our findings are limited to our mouse model and not representative of the host response in humans, although both species showed significant IL-6 induction following infection." (PMID 22679491, 2012). "One of the most prominent chemokines in the air pouch lavage was IL-6, a proinflammatory chemokine with prognostic value for severity of infection." (PMID 22848376, 2012). "Ample studies conducted have provided strong evidences that by blocking TF, the proinflammtory cytokine elaboration (IL-6, IL-8), levels of soluble TNF receptor-1 and infection-associated organ injury and mortality were reduced." (PMID 23029190, 2012). "The early cytokine responses (TNFα, IL-6, IL-1β, IL-12) were measured on the first day of low-dose or high-dose infection." (PMID 23028333, 2012). "The levels of the chemokines KC, MIP-1α, MIP-2, and the pro-inflammatory cytokines IL-1β, IL-6 and TNFα further increased and peaked at day 2 of infection." (PMID 22347396, 2012). "Both IL-1β and IL-6 promote Th17-cell differentiation, therefore implying that primary mouse infection with human as well as avian schistosomes induces a Th17 polarized response." (PMID 23125918, 2012).
infection (continued). "Upregulated levels of IL-6 are related to increased responses to infection, such as fever, phagocytic cell recruitment, and blood vessel permeability." (PMID 22911786, 2012). "Interleukin-6 (IL-6) is a cytokine that is produced during inflammation and that plays an important role in host defenses to invasive infection." (PMID 22919407, 2012). "IL-6 is a member of a family of mediators involved in regulation of the acute-phase response to injury and infection and inflammation, and chronic elevations in IL-6 are thought to represent a state of atherosclerotic inflammation." (PMID 22808178, 2012). "Further, BP-induced significantly higher levels of pro-inflammatory cytokine secretion from ATII cells (IL-6, IL-8) and macrophages (IL-6, TNFα) at 6 h post-infection compared to BM (p < 0.05)." (PMID 23293773, 2012). "Meanwhile, infection with the wb cluster-complemented A4528 wbbO mutant stimulated IL-6 production to levels higher than those seen with the A4528 wbbO mutant (P = 0.002)." (PMID 22427976, 2012). "In contrast, IL-8 and IL-6 cytokines were detected as early as 1 day after infection in day-2 infected cell-culture supernatants, suggesting the induction of cellular signaling pathways that lead to a rapid increase in the expression of these mediators." (PMID 22529524, 2012). "In contrast, the infection control group (S) significantly increased IL-6 secretion during all the experiment, compared with basal data." (PMID 21813005, 2011). "In this study, we detected stronger upregulation in the gene expression of IL-6 in the bursa of cIBDV-infected chickens than vIBDV-infected chickens during the early stage of infection." (PMID 21749706, 2011). "Similar to wild type Nippo mice, mast cell-reconstituted Wsh-Nippo mice had higher levels of IL-6 in peritoneal lavage fluid compared to mast cell-reconstituted Wsh control mice 4 h after infection with Klebsiella (124 vs. 65.4 pg/mL)." (PMID 22110673, 2011). "Nevertheless, this increase remains much lower than that observed in immunocompetent mice upon lethal VACV or CPXV infection for which, in comparison with uninfected controls, a 60-fold increase in IL-6 concentrations has been recorded." (PMID 21738709, 2011). "ChemR23−/− mice displayed higher levels of IL-6 than WT mice at day 8 and the difference became significant at day 9 (1447±664 versus 288±38 pg/ml respectively, p<0.01) and day 10 post-infection (1301±328 versus 454±124 pg/ml respectively, p<0.05)." (PMID 22072972, 2011). "Further, IL-6 expression was increased at 21 days post-infection for granule neurons expressing the miR-132 sponge compared to control neurons expressing only mCherry." (PMID 21611182, 2011). "Infection of DCs from each donor (n = 3) with H37Ra consistently stimulated the release of pro- and anti-inflammatory cytokines including TNFα, IL-6, IL-8, IL-10, IL-1β and a modest increase in secretion of IL-12p70." (PMID 22024399, 2011). "IL-6 demonstrated a high potential with the ability to detect the cases at very early stage of infection and monitor the appropriateness of therapy, based on its characteristic early appearance and short half life." (PMID 23198119, 2011). "Expression of IL6 by non-proliferating cells is consistent with the observation that only rare EBV-immortalized tonsillar blasts expressed IL6 during primary infection." (PMID 21352549, 2011). "IL6 plasma levels are raised by infection with C. pneumoniae or Helicobacter pylori, and IL6 production in monocytes is stimulated by C. neoformans." (PMID 22254144, 2011). "Up-regulated levels of IL-1, IL-6, IL-12, and IL-23 were reported to be related to increased responses to infection, such as fever, phagocytic cell recruitment and blood vessel permeability." (PMID 22174866, 2011). "The acquisition of IL-17A production by 2W:I-Ab-specific T cells and the capacity of mice to survive infection depended on the innate cytokine IL-6." (PMID 21966268, 2011).
infection (continued). "The addition of LL37 (3 μM) to the infection medium enhanced IL6 production above that of RV infection by 1.6 ± 0.04 fold (p<0.002; n = 3), IP10 production by 2.8 ± 0.3 fold (p<0.005, n = 3) and MCP-1 by 2.4 ± 0.1 fold (p = 0.003, N = 3)." (PMID 22039520, 2011). "IL-6-/- mice that survived the first week of infection returned to health even though they retained significant numbers of GAS-2W organisms in NALT." (PMID 21966268, 2011). "IL-6 is a pleiotropic cytokine which has been shown to be overexpressed in response to infection, injury and inflammation." (PMID 21526200, 2011). "In contrast, 3h following infection, TNFα and IL-6 transcripts in the lungs of Ncr1gfp/gfp mice were significantly higher compared to the transcripts of these cytokines in Ncr1+/gfp mice." (PMID 21887255, 2011). "Poly(I-C) induction of genes involved in alerting the innate immune system to the infectious threat, including TNF-alpha, IL-1 alpha and beta, CCL5 and IL-6, were suppressed by infection with live MPV." (PMID 21267444, 2011). "A 4-fold increase in the levels of IL-6 was recorded upon i.n. infection, albeit only low levels of IL-6 were detected (mean levels of 20 pg/ml), compared with uninfected controls." (PMID 21738709, 2011). "Both viruses up regulated the IL-1β and IL-6, after infection in turkey cells, although the H5N9 stimulated a more robust response." (PMID 21939525, 2011). "The finding that Nippo mice have higher intraperitoneal IL-6 levels 4 h after infection and that IL-4-conditioned mast cells generate more IL-6 is consistent with the idea that mast cells are a source of the higher IL-6 levels in Nippo mice." (PMID 22110673, 2011). "There were higher concentrations of TNF-α and IL-6 in spleen and more severe hepatic injury in IL-12p40−/− than WT mice after infection." (PMID 22206036, 2011). "Control cells and calpastatin- or calpain-overexpressing NIH-3T3 cells (infection efficiencies were >95%) were stimulated with LPS or IL-17, and the IL-6 concentration in the culture supernatants was measured by ELISA." (PMID 22046434, 2011). "Levels of the cytokine IL-6 were twenty-fold higher the first day after infection with HSV-2/gD-Δ7-15 relative to HSV-2/gD." (PMID 21283640, 2011). "The levels of IFN-γ and IL-6 have been reported to be directly proportional to the severity of infection in S. Dublin infected mice." (PMID 21347426, 2011). "Production of interleukin-6 (IL-6), another hematopoietic cytokine, has been positively influenced by soluble β-glucan in mice infected by Listeria monocytogenes in which the level of IL-6 was decreased by the infection." (PMID 21921869, 2011). "Cord blood proinflammatory cytokines IL-6 and IL-8 are used as a marker of early-onset infection in premature infants." (PMID 20940111, 2011). "Upon initial infection with mycobacteria, macrophages secrete multiple cytokines and chemokines, including interleukin-6 (IL-6), IL-8 and tumor necrosis factor-α (TNF-α), to mediate host immune responses against the pathogen." (PMID 21447195, 2011). "Interleukin (IL)-6 is produced in the brain during peripheral infection and plays an important but poorly understood role in sickness behavior." (PMID 21595956, 2011). "Several potential biomarkers of infection have been assessed in the evaluation of febrile neutropenic patients, like interleukin (IL)-6, IL-8, serum amyloid A, C-reactive protein (CRP), procalcitonin, with diverse results." (PMID 21595932, 2011). "In comparison with that in the wild-type virus infected mice, infection with the mouse-adapted viruses, particularly with MA-8 (p<0.01), promoted significantly higher levels of IL-6, MCP-1, and G-CSF, but dramatically reduced levels of IFN-γ in BALF (P<0.05)." (PMID 22194944, 2011). "When IP-10 concentration was combined with various other markers of infection such as IL-6, IL-8, and IL-10, the sensitivity and NPV were slightly improved by up to 7%, but the specificity and PPV were dramatically decreased by up to 50%." (PMID 23198120, 2011).
infection (continued). "The experiment of infection realized with the strain M. paratuberculosis 1515 and enteric glial cells showed a production of IL-1A and IL-6 already after 24 hours after the infection, until the achievement of a plateau after 48 hours." (PMID 22151930, 2011). "Our results demonstrate that an intranasal infection is critical for mounting an effective IL-6-dependent pMHCII-specific Th17 response." (PMID 21966268, 2011). "Bovine macrophages produced elevated IL-6 mRNAs following infection with B. abortus; however, this response was accelerated and amplified by γδ T cells." (PMID 21765931, 2011). "IL-6 and KC were detected in the brain fraction only in infected congenic transgenic mice after 6 h of infection." (PMID 21811575, 2011). "This raised the possibility of viral persistence or secondary infection resulted from immunosuppression mediated synergistically by IL-6 and IL-10." (PMID 22174866, 2011). "Surprisingly, upon stimulation with Δ-mce1 H37Rv the concentration of all cytokines measured, except for IL-6, remained similar to that of the uninfected controls during the first hour post-infection." (PMID 22039457, 2011). "Both viruses tested up regulated the proinflammatory cytokine genes, IL-1β and IL-6, after infection." (PMID 21939525, 2011). "Although A/J mice succumb to C. albicans infection early after infection (48 h), they mount a similar Th2-like cytokine storm consisting of high levels of IL-6, IL-10 and TNFα, suggesting a common role for C5 in both pathologies." (PMID 22206032, 2011). "This serotype 3 data is accordance with induction of IL-6 observed here, which was detected after 24 hours of infection." (PMID 21483672, 2011). "The acute phase cytokines, TNF-α and IL-1βand chemokine IL-8 levels increase within 2 h following infection, while IL-6 expressed late, at 8 to 16 h post infection." (PMID 21249123, 2011). "The number of IL-6 (+) cells was significantly increased (p < 0.01) in the three groups challenged with the pathogen 7 days post infection, compared to the untreated control group (C)." (PMID 21813005, 2011). "Taken together, these results suggest an imbalance between the inflammatory (increased release of IL-6) and anti-inflammatory (increased release of IL-10) responses in acute phase of infection in aged patients." (PMID 20716329, 2010). "This revealed a sharp decline in IL-6 transcripts during the first 24 hours following infection by PRRSV." (PMID 22331987, 2010). "Compared to WT Mtb, infection of primary macrophages with Tn:Rv0431 resulted in secretion of much larger amounts of IL-10, IL-6, MCP-1, IL-12p40 and TNFα as judged by ELISA and higher levels of transcripts for GM-CSF and COX-2 as measured by qRT-PCR." (PMID 21170273, 2010). "The same was observed upon infection by MHV-68 highlighting the importance of the TLR2-MyD88 pathway for IL-6 secretion in response to the virus." (PMID 21060793, 2010). "Elevated levels of LBP, IL-6 and CRP were associated with a more severe level of infection in children." (PMID 20158885, 2010). "TLR2-dependent IL-6 production was detected as early as 6 hours post-infection and was sustained at 18 and 24 hours." (PMID 21060793, 2010). "Systemic injection of LPS induces fever and septic shock and is associated with an increase of different cytokines, including TNF-α, IL-1β and IL-6, in the blood circulation and in the brain in a pattern similar to that seen in natural infection." (PMID 21067602, 2010). "TNF-alpha, IL-6 and IL-10 expression was also modulated upon infection showing a TLR2-specific dependent IL-10 secretion." (PMID 20523725, 2010). "At 18 hours post-infection, IL-6, CCL-5/RANTES and CXCL-10/IP-10 were highly expressed (12 to >1000 folds) in H5N1/2004 infection." (PMID 21108843, 2010). "Four hours after infection with 105 LSE, TLR2-deficient macrophages also demonstrated diminished production of IL-6, as well as the chemokines CXCL1 and CXCL2." (PMID 20404927, 2010).